TNF (tumor necrosis factor)
Diseases named in the same sentence as TNF in open-access papers (continued):
Sharing a sentence is not in itself a finding about the gene and the disease.
lymphoma (continued). "Therefore, P-selectin and TF were predictors of clinical stage progression, while TNF-α was predictor of IPI in lymphomas." (PMID 40076681, 2025). "Therefore, a confounding aspect in the development of lymphoma in anti TNF-α treated HS can be discussed." (PMID 39046819, 2024). "In adults, the use of thiopurine monotherapy or anti-TNF therapy alone has been associated with an increased risk of developing lymphoma when compared to patients who are not receiving these drugs." (PMID 38673824, 2024). "Although some studies have hinted at a possible elevated risk of lymphoma in specific subgroups, the overall evidence does not support a definitive conclusion regarding any such risk with anti-TNF-α therapy." (PMID 39064585, 2024). "In Hodgkin’s lymphoma cells, LT4, CAM29, and MN8 act to reduce the release of ADAM10 substrates (CD30 and TNF-α), lower the ATP content of lymphoma cells, and increase the release of lactate dehydrogenase, ultimately inhibiting the growth and proliferation of lymphoma cells." (PMID 39634655, 2024). "In a recent systematic review and meta-analysis including four observational cohort studies totaling 261,689 IBD patients an incidence rate of lymphomas of 0.34 per 1000 patient-years (95% CI: 0.30–0.37) was found in patients unexposed to either anti-TNF or thiopurines." (PMID 36765708, 2023). "According to the prospective, 5-year, observational ENCORE registry, no excess risk of lymphoma was observed in patients diagnosed with IBD treated with anti-TNF agents alone." (PMID 37206474, 2023). "Recently, an increased risk of cancer, especially for non-melanoma skin cancer and lymphoma, was described in patients taking anti-TNF-α agents compared with the control population." (PMID 36836166, 2023). "The INF-γ and TNF-α levels of lymphoma patients were higher than those of healthy controls." (PMID 35432366, 2022). "In addition, side effects, including opportunistic infections, lymphoma, malignancies progression, and skin damage, should be deliberated when administering anti-TNF-α." (PMID 36687438, 2022). "This may be because IFN-r and TNF-α are closely related to the occurrence and development of lymphoma, which is consistent with the results of a previous study." (PMID 35432366, 2022). "The risk of incident lymphoma in patients with IBD receiving anti-TNF therapy remains controversial because few patients receive anti-TNF monotherapy; most of them are treated with thiopurines alone or combined with immunosuppressants and anti-TNF agents." (PMID 36389673, 2022). "Additionally, TNF-α levels were higher in lymphoma from children compared with their solid-tumor counterparts, which suggests the relevant role of this protein in lymphomas." (PMID 36555171, 2022). "Thus, we studied the expression of TNF-α and IL-10 as Th1 and Th2 mediated cytokines, respectively, involved in lymphoma patients in Iraq, especially given the high incidence of blood disease in this country." (PMID 35928372, 2022). "A study of 12,656 cases of incident RA from a Swedish registry also reported no impact of TNF inhibitors on the risk of lymphoma." (PMID 33535498, 2021). "It is important not to forget that recent reports suggest that the risk of lymphoma is comparable for TP and anti-TNF drugs." (PMID 34336887, 2021). "The risk of lymphoma in IBD patients seems to be related to the treatment more than to the disease itself, in particular with thiopurines and to a lesser extent with anti- tumor necrosis factor α (anti-TNFα)." (PMID 34572754, 2021). "Also, in BCL6-driven lymphomas, inhibition of autophagy through BCL6-mediated transcriptional repression of LITAF (lipopolysaccharide (LPS)-induced TNF alpha (TNFα) factor) has been proposed to be implicated in their pathogenesis." (PMID 34782660, 2021). "Similar with previous report on lymphoma cells, TNFα treatment could upregulate the expression of PIM2 in a dose dependent manner on both QSG7703 and BEL7402 cells." (PMID 32641749, 2020).
lymphoma (continued). "TNFα is a major mediator of inflammation with ambiguous effects and has been detected in human ovarian, breast, endometrial, oral, pancreatic, gastric, liver, prostate, bladder and colorectal cancer as well as in lymphomas and leukemias." (PMID 32391269, 2020). "High values of TNF-α serum levels in lymphoma were explained by many studies." (PMID 30814315, 2019). "On the other hand, to prevent the risk and recurrence of lymphoma associated with anti-TNFα Abs for RA patients, rituximab (anti-CD20 Ab, Mabthera) was recommended to replace anti-TNFα Abs, which can be a dual agent that inhibits the progression of lymphoma and RA disease activity." (PMID 31194726, 2019). "Our patient could represent a case of primary intraocular lymphoma, possibly related to the use of the anti-TNFα agent etanercept." (PMID 29954352, 2018). "The results of this study align with those of previous analyses of lymphoma in users of anti-TNF." (PMID 27502891, 2017). "This national prospective study, with over 120 000 pyrs of exposure to anti-TNF or csDMARD, did not identify any difference in lymphoma risk for up to 8 years after the addition of TNFi to the standard treatment regimen of patients with RA." (PMID 27502891, 2017). "The higher risk of lymphoma in RA patients treated with TNF-α inhibitors has been suggested but not clearly demonstrated." (PMID 28222785, 2017). "In addition, polymorphism in the predicted enhancer region of the bovine TNF-α (tumor necrosis factor, allele −824G associated with low transcription activity) was shown to contribute in the progression of BLV-induced lymphoma." (PMID 27812893, 2017). "However, the low frequency of detection led to the conclusion that TNF-α has limited value as a biomarker for lymphoma." (PMID 27747218, 2016). "Lymphoma is associated with cumulative RA disease activity and registry data have not shown an association between TNF inhibitor treatment and increased lymphoma risk." (PMID 25627338, 2015). "Several reports have indicated that patients receiving anti-TNF antibody therapy had no significantly increased risk of developing malignant lymphoma." (PMID 24721419, 2014). "However, a study comparing published case reports and reports from the French pharmacovigilance system has argued the link between lymphoma and TNF-α antagonists." (PMID 25267341, 2014). "The rationale for treatment of lymphoma with a TNF inhibitor is still unclear." (PMID 24721419, 2014). "Patients with severe RA on anti-TNFα treatment may in rare cases develop concurrent lymphoma and another primary tumor." (PMID 23320919, 2013). "Evidence from observational cohort studies using more than 15,000 patients found no increased risk of lymphoma or any solid tumors in patients with RA receiving anti-TNFα treatment, although RA was more severe in the group receiving the biological treatment." (PMID 23320919, 2013). "In summary, neither has a causal relationship between anti-TNFα therapy for RA and lymphoma been established or ruled out." (PMID 23320919, 2013). "Some recent large population studies have shown no additional risk of lymphoma conferred by TNF inhibitors in RA patients." (PMID 20712883, 2010). "The increased lymphoma rates observed with anti-TNF therapy may reflect channeling bias, whereby patients with the highest risk of lymphoma preferentially receive anti-TNF therapy." (PMID 27942275, 2009). "IL-10 and TNFα are well-known growth factors for lymphoma and myeloma cell lines." (PMID 19956602, 2009). "Results for three large cohorts of RA patients did not reveal any increased risk of lymphoma in RA patients receiving anti-TNF drugs versus RA patients receiving classical disease-modifying anti-rheumatic drugs (DMARDs)." (PMID 19470150, 2009). "Although anti-TNF agents were previously suspected to be associated with an increased oncogenic risk, in particular lymphoma and NMSC, such a hypothesis has not been confirmed by subsequent evidence." (PMID 40507276, 2025).
lymphoma (continued). "In addition, lipopolysaccharide (LPS) in the resident microbiota of lymphoma patients and mice interacted with TNF signal and enhanced the NF-kB pathway through MyD88-dependent TLR4 signal, which also enhanced the survival and proliferation of intestinal B cells." (PMID 37190210, 2023). "Lymphomas and non-melanoma skin cancers may be associated with Anti-TNF agents as well, results from the ARTIS program." (PMID 37182186, 2023). "Furthermore, it has been hypothesized that the lymphoma cells mediate their spindling process by secreting specific cytokines, including TNF-α, platelet-derived growth factor (PDGF) and transforming growth factor (TGF) -β." (PMID 36975591, 2023). "Notably, other studies have not found an independent association between anti-TNF therapy and lymphoma risk." (PMID 37674502, 2023). "In particular, an increased risk of lymphoma in patients with systemic inflammatory diseases taking TNF-α inhibitors could be a result of the disease process and not the effect of immunosuppressive therapy." (PMID 36836166, 2023). "The potential safety advantage of non-anti-TNF biologics over anti-TNF therapies may disappear if these non-anti-TNF drugs are used in combination with thiopurines, which increases the risk of infections and lymphomas." (PMID 35160280, 2022). "It is important to note that patients with combination therapy (thiopurine plus anti-TNF) seem to have a significant increase in the risk of lymphoma (up to 6-fold compared with nontreated patients and 2.5-fold compared with patients treated with thiopurines or anti-TNF monotherapy)." (PMID 35160280, 2022). "Therefore, we next determined whether levels of perforin, granzyme B, or cytokines TNF-α or IFN-γ would be affected by exposure of NK cells to lymphoma exosomes or survivin protein." (PMID 33513976, 2021). "DOX combined with SM can enhance the anti-tumor effect, and induce apoptosis of lymphoma cells and inhibit the expression of inflammatory factors related to tumorigenesis depending on the regulation of Bcl-2 family-mediated mitochondrial pathways, such as TNF-α and IL-1β." (PMID 34120620, 2021). "Notably, a recent overview of systematic reviews and meta-analyses of malignancy risk with TNF inhibitors noted no increase in lymphoma risk in patients with RA." (PMID 33535498, 2021). "Anti-TNF-α may potentially induce severe side effects, including viral and bacterial infections, severe anaphylactic reactions, demyelinating neurological disorders, and the development of tumors (especially lymphoma)." (PMID 32069898, 2020). "Also, we found an evidence for the diagnostic utility of the following markers: MCP-1, eotaxin, IL-10 and IL-6 for NHL and HL and IL-1β for HL, while TNF-α has limited utility due to the poor ability to discriminate amongst patients with lymphoma and healthy control, as well as IL-1β for NHL." (PMID 30814315, 2019). "A recent systematic review of 49 studies showed that RA patients who used a TNF-inhibitor did not have an additional increased risk for malignancies in general, nor for lymphoma or non-melanoma skin cancer as compared to RA patients who did not use a TNF-inhibitor." (PMID 27118031, 2016). "However, the use of anti-TNF or anti-TNF receptor recombinant fusion monoclonal antibodies (infliximab, etanercept) should be avoided in NBS because of already present high risk for lymphoma." (PMID 24044622, 2013). "Our assay may be valuable for estimating the effectiveness of vaccination and may also be capable of detecting changes in proviral load in BLV-infected cattle with the TNF and BoLA alleles that have previously been associated with resistance or susceptibility to BLV-induced lymphoma." (PMID 21044304, 2010). "It turned out that C5a, TNF-α, growth-related oncogene (GRO)-a, CCL1/I-309, and interleukin-6 significantly promoted the proliferation of lymphoma cell lines when co-cultured with M2 macrophages." (PMID 41030738, 2025).
lymphoma (continued). "Stromal cells, including follicular dendritic cells and macrophages, secrete cytokines and chemokines such as IL-10, TNF-α, and CXCL12, which enhance lymphoma cell survival and proliferation." (PMID 41180747, 2025). "Lymphoma cells secrete TNF‐α, which enhances TLR4‐mediated signaling in intestinal B cells and in turn inhibits malignant growth of lymphoma." (PMID 40727252, 2025). "To observe the risk of thrombosis in hematologic malignancies, we examined the levels of inflammatory factors IL-1β, TNF-α, TGF-β, and MCP-1 as well as coagulation factors FVIII, TF, P-selectin, thrombin, and fibrinogen in the plasma of patients with lymphoma." (PMID 40076681, 2025). "Plasma exosomes from EBV-infected lymphoma cells, which mainly contain BART-miRNAs, function similarly to pro-inflammatory cytokine to trigger the secretion of ARG1, TNF-α, and IL-10 in monocytes and macrophages." (PMID 36411555, 2024). "Specifically, it prevents lymphoma by modulating the TNF-induced TLR4/MyD88/NF-κB axis, thereby reducing lymphoma incidence in Eμ-Myc mice." (PMID 39619672, 2024). "In vitro cytotoxicity and cytokine secretion assays (IFN-γ and TNF-α) confirmed the specificity of gp350CAR-T cells against gp350+ NPC, GC and lymphoma cell targets." (PMID 36817460, 2023). "In general, myeloma patients showed a reduced T cell activation via CD3/CD28 compared to lymphoma patients, especially for IFN- and TNF-producing T cells." (PMID 37187728, 2023). "In summary, here, we show that, in spite of the similar anti-lymphoma activity, AWARI CAR-T cells exhibit a milder secretion of TNF-α and IFN-ɣ as well as reduction in LAG-3 expression, both important players in CRS." (PMID 35694446, 2022). "For lymphoma patients with NHL and HL, TNF-α and IL-10 levels were higher than normal levels before RSV treatment." (PMID 35928372, 2022). "The inhibition of LPS-induced TNF-α expression in macrophages has been shown to be mediated by IL-10, the expression of which is promoted by BCL3 (B-Cell Leukemia/Lymphoma)." (PMID 32759853, 2020). "Therefore, as Chen and colleagues pointed out, systemic targeting of TNF-α with anti-TNF-α mAbs such as Remicade and Humira is known to create a higher risk of serious infections, and long-term treatment with Remicade may increase lymphoma incidence." (PMID 30469350, 2018). "Several factors may hinder a definitive correlation between anti-TNF-α therapy and lymphoma development, among which the selection of the population enrolled in different studies or national registries and the inter individual variability of the immune system exposed to TNF-α." (PMID 28222785, 2017). "Expression of B cell-stimulatory cytokines IL-1β, IL-6, IL-10, IL-12p40, IL-13 and TNFα and HIV proteins p17, gp120 and nef were elevated in the Tg mice with lymphoma." (PMID 23985023, 2013). "In light of this information, RTX can become an alternative treatment option in the near future for AS patients for whom TNF-blockers are contraindicated, for example, because of TBC, lymphoma, or demyelinating disease." (PMID 24324911, 2013). "In response to reports of lymphomas through post-marketing surveillance, the Food and Drug Administration (FDA) summarised data from clinical trials for all TNFα inhibitors." (PMID 23320919, 2013).
lymphoma (continued). "TNF-α was generally in negative correlation with IPI in lymphomas (ρ = −0.448) and DLBCL (ρ = −0.426) with thrombosis." (PMID 40076681, 2025). "Studies revealed that relative to patients who had not been exposed to anti-TNF-α, those receiving anti-TNF-α monotherapy had a pooled Incidence Rate Ratio (IRR) of lymphoma of 1.52 per 1000 patient-years (95% CI: 1.06–2.19; p = 0.023)." (PMID 40283885, 2025). "This means that if the diagnosis of lymphoma was made a few days after initiating anti-TNF drug treatment, the adverse event was attributed to the anti-TNF group, even though the result was not reliable." (PMID 38673824, 2024). "An excess of BAFF in the absence of protective tumor necrosis factor (TNF) leads to a high incidence of lymphoma in BAFF transgenic mice, suggesting that BAFF functions in promoting B-cell malignancy." (PMID 38482011, 2024). "The use of thiopurine and anti-tumor necrosis factor-α (anti-TNF-α) drugs further increases the risk of non-melanoma skin cancer (NMSC) and lymphoma." (PMID 39001273, 2024). "In the present study, it was not possible to draw conclusions due to lack of information on the occurrence of lymphoma in patients treated with anti-TNF agents." (PMID 37206474, 2023). "Meanwhile, for patients with the absence of anti-tumor necrosis factor (TNF) and/or thiopurine, the risk of developing lymphoma is relatively decreased." (PMID 37593734, 2023). "On the contrary, a recent review of observational data was unable to identify or rule out any link between lymphomas and anti-TNF medication in IBD patients." (PMID 37206474, 2023). "Neither the duration of exposure to thiopurines nor anti-TNF was correlated with age at diagnosis of lymphoma." (PMID 36765708, 2023). "In conclusion, most IBD patients had been treated with thiopurines and/or anti-TNF agents before lymphoma diagnosis, and these patients were younger at diagnosis of lymphoma than those not treated with these drugs." (PMID 36765708, 2023). "Age at lymphoma was lower in those patients treated with thiopurines (53 ± 17 years old) and anti-TNF drugs (47 ± 17) than in those patients not treated with these drugs (63 ± 12; p < 0.05)." (PMID 36765708, 2023). "The levels of IL-10 and TNF-α for the patient without lymphoma (26.3, 257 pg/ml) were lower than those of all samples involved in the study." (PMID 35928372, 2022). "Unlike that for infliximab and adalimumab, which are widely used in IBD patients, no data on the risk associated with therapy with other anti-TNF agents, such as golimumab and certolizumab pegol, in IBD patients complicated with lymphomas have been available." (PMID 36389673, 2022). "The lowest resveratrol concentration (50 μg/ml) decreased TNF-α levels for patients without lymphoma and all NHL patients in contrast to the HL sample." (PMID 35928372, 2022). "Three RSV concentration levels were subjected to isolated lymphocytes from blood samples of Hodgkin lymphoma (HL), non-Hodgkin lymphoma (NHL), and without lymphoma to estimate the change in TNF-α and IL-10." (PMID 35928372, 2022). "The BAFF-R is a pro-survival receptor expressed on B-cells and a large proportion of malignant B-cells that plays an important role in the proliferation of both normal B-cells and malignant lymphoma in response to BAFF, a member of the tumor necrosis factor (TNF) family of ligands." (PMID 34680329, 2021). "Alternatively, cytokines such as IL-1, IL-6, TNF-α, and TGF-β, secreted directly by lymphoma cells, may lead to tubular injury and interstitial fibrosis." (PMID 34218814, 2021).